RN7SKP171 (RN7SK pseudogene 171)
Gene: Miscellaneous RNA gene on chromosome 9 (37,661,747 to 37,662,049, reverse strand). Ensembl gene ENSG00000201287.
Homologues: Orthologues: chimpanzee 7SK (86% identical). Paralogues in human: RN7SKP71 (80% identical), RN7SKP69 (78% identical), RN7SKP255 (77% identical), RN7SKP176 (77% identical), RN7SKP9 (77% identical), RN7SKP204 (77% identical), RN7SKP79 (76% identical), RN7SKP146 (75% identical), RN7SKP203 (75% identical), RN7SKP243 (75% identical), RN7SKP128 (75% identical), RN7SKP180 (75% identical), and 284 more.